FGFR2 (fibroblast growth factor receptor 2)
Diseases named in the same sentence as FGFR2 in open-access papers (continued):
Sharing a sentence is not in itself a finding about the gene and the disease.
ovarian carcinoma (25 papers, 2007 to 2025). A malignant neoplasm originating from the surface ovarian epithelium. "The effect of polymorphisms on the family history of cancer was also reported by Huijts and collaborators, who showed an association between rs2981582 in gene FGFR2 and the average number of first- and second-degree relatives with breast and/or ovarian cancers (P = 0.05)." (PMID 26770289, 2016). "Another rare but tumor-specific ctDNA variant, the fibroblast growth factor receptor 2 (FGFR2) fusion gene, has been identified as a potential biomarker for monitoring treatment response in advanced ovarian cancer." (PMID 40507303, 2025). "Reduction of FGF7 and/or FGFR2 using shRNAi in ovarian cancer cell lines and tumors inhibited growth and increased cisplatin sensitivity." (PMID 39886662, 2024). "As an example, FGFR2 (fibroblast growth factor receptor 2) was monitored using ctDNA in a patient treated for an ovarian cancer and carrying a fusion transcript involving this gene." (PMID 31167492, 2019). "Preclinical data justifies targeting the FGF7/FGFR2 pathway in ovarian cancer." (PMID 39886662, 2024). "In addition to this potential for developing ovarian cancer therapies targeted at FGF7/FGFR2-IIIb, FGF7 has potential for being used as a biomarker of patient prognosis and sensitivity to FGFR inhibitors." (PMID 39886662, 2024). "The exceptional case was the FGFR2-LGSN fusion from the ovarian cancer sample OC11." (PMID 36009413, 2022). "In addition, the microarray study has detected aberrant AS of genes in ovarian carcinomas, including FGFR2, DNNP3B, KITLG, MDM2 and MRP123." (PMID 34001978, 2021). "An allosteric inhibitor of FGFR2 IIIb and the alternatively spliced FGFR2 IIIc, alofanib, induced apoptosis in the SKOV3 ovarian cancer cell line and reduced growth of SKOV3 xenograft tumors in association with inhibition of angiogenesis." (PMID 39886662, 2024). "Treatment of ovarian cancer cell lines with FGF7 increased invasion, while an antagonistic FGFR2-IIIb antibody reduced basal and FGF7-elevated invasion." (PMID 39886662, 2024). "One study identified the fibroblast growth factor receptor 2 (FGFR2), the receptor for FGF10, as a target of miR-628-5p in ovarian cancer cells." (PMID 33807742, 2021). "FGFR2 and FGFR3 are highly expressed in ovarian cancer tissues and their expression level is correlated with the poor survival outcome of patients with ovarian cancer." (PMID 34639155, 2021). "For example, Cole C. with the co-authors found the inhibition of FGFR2 and/or FGF-3 and -7 substantially reduced the proliferation of ovarian cancer cells and reduced the IC50 for cisplatin in vitro." (PMID 31948066, 2020). "From the total of 34 ligand and receptor genes identified in these interactions, seven (COL1A1, ITGB5, COL1A2, FGFR2, FN1, IGF1, and IGF2) were consistently up-regulated and predicted worse overall survival in two additional cohorts (TCGA and GSE9891) of ovarian cancer patients." (PMID 36352420, 2022). "We observed the upregulation of FGFR2 and FGFR3 expression in patients with ovarian cancer." (PMID 34639155, 2021). "Based on knowledge of the FGF7/FGFR2-IIIb interaction, bemarituzumab, which specifically targets FGF7’s receptor FGFR2b, would be of particular interest and may serve as a promising agent for future use in ovarian cancer." (PMID 39886662, 2024). "Furthermore, drug sensitization produced by silencing of these txr genes could also be found in the ovarian carcinoma cell lines MDAH-2774 and TOV21G, as seen for example when FGFR2 was silenced (SF50=1.3 and 2.2, respectively)." (PMID 26318424, 2015).
cervical carcinoma (22 papers, 2013 to 2025). A carcinoma arising from either the exocervical squamous epithelium or the endocervical glandular epithelium. "Studies demonstrate a similar link between somatic oncogenic FGFR2 mutations in EC as with cervical cancer." (PMID 35269800, 2022). "BRCA1, ESR1, PCNA, and FGFR2 have already been shown to be associated with cervical cancer." (PMID 30020984, 2018). "In the meantime, studies have exposed that miR-889-3p targets FGFR2 to inhibit the activity and invasion of cervical cancer cells." (PMID 34723781, 2021). "Usingin vitro knockdown experiments for two out of 14 differentially co-expressed genes found in cervical cancer (FGFR2 and CACYBP), we showed that they play regulatory roles in cancer cell growth." (PMID 28163897, 2016). "Our study suggested that somatic mutations in EGFR, FGFR2, and FGFR3 are rare in cervical cancers; this result was similar to the findings of previous studies." (PMID 25669975, 2015). "Being 16E5 a very early expressed protein during HPV16 infection, this work encouraged us to propose that, at least in cervical cancer, the altered FGFR2 splicing and the consequent appearance of FGFR2c might play an important role in early tumor development." (PMID 26713601, 2016). "In conclusion, the present study investigated the immunohistochemical expression of FGFR1, FGFR2, FGFR3, and FGFR4 in a large number of cervical cancer patients." (PMID 27154171, 2016). "Cox regression analysis confirmed that FGFR2, FGFR3, and FGFR4 expression was an important prognostic indicator in cervical cancer." (PMID 27154171, 2016). "In the present study, we investigated the prognostic significance of FGFR1, FGFR2, FGFR3, and FGFR4 expression in a large cohort of cervical cancer patients." (PMID 27154171, 2016). "Although there is the heterogeneity of HPV-related tumors at different anatomical sites, alteration of FGFR2 and FGFR3 could also be worthwhile to study in cervical cancers." (PMID 27154171, 2016). "In order to test if FGFR2 and CACYBP play critical regulatory roles in cancer pathogenesis, we evaluated the effect onin vitro knockdown of these genes on cell proliferation in a cervical carcinoma cell line." (PMID 28163897, 2016). "In addition, we have tested two DC genes and confirmed their regulatory role (FGFR2 as a tumor suppressor and CACYBP as a potential oncogene in cervical cancer) by manipulating their expressionin vitro." (PMID 28163897, 2016). "Furthermore, we demonstrate for the first time that elevated expression of FGFR2, FGFR3, or FGFR4 predict favorable survival in cervical cancer patients." (PMID 27154171, 2016). "Thus, the aim of this study is to investigate the clinical significance of FGFR1, FGFR2, FGFR3 and FGFR4 expression in a well-defined cohort of cervical cancers, using immunohistochemistry and quantitative digital image analysis." (PMID 27154171, 2016). "FGFR1, FGFR2, FGFR3, and FGFR4 expression was determined by immunohistochemistry in conjunction with quantitative digital image analysis of 336 formalin-fixed, paraffin-embedded cervical cancer tissues and 61 normal cervical tissues, as well as NCI60 cell microarray." (PMID 27154171, 2016). "Therefore, for validation experiments we chose one down-regulated (FGFR2) and one up-regulated (CACYBP) gene that have not been previously studied in cervical cancer for regulatory properties, but have a potential connection with cell death or proliferation based on their Gene Ontology annotations." (PMID 28163897, 2016).
gastric adenocarcinoma (22 papers, 2013 to 2025). "Bemarituzumab, an afucosylated mAb against FGFR2b, induced confirmed objective responses in 5 (18%) out of 28 patients with CHT-refractory gastric adenocarcinoma characterized by FGFR2 amplification and elevated FGFR2b overexpression." (PMID 39941712, 2025). "In the second case (19-year-old female with gastric adenocarcinoma), a similar plasma profile was observed with FGFR2 amplification (copy number 82.6) and a low-level WDR11-AS1–FGFR2 fusion (0.1% VAF)." (PMID 41357601, 2025). "The patient with gastric adenocarcinoma had a tumor expressing programmed cell death-ligand 1 (PD-L1) and showing a fibroblast growth factor receptor 2 (FGFR2) amplification." (PMID 40264106, 2025). "The presence of FGFR2 expression or amplification seems to be one of the patient selection factors for targeted therapy of gastric adenocarcinoma." (PMID 38155920, 2023). "We observed an FGFR2 fusion from the ASC supernatant in gastric adenocarcinoma and a RET fusion in colon adenocarcinoma tissues." (PMID 36167530, 2022). "A recent phase II trial selected patients with advanced gastric adenocarcinoma and FGFR2 polysomy or gene amplification (via FISH) to receive AZD4547 or paclitaxel." (PMID 33105560, 2020). "Among all the selective FGFR inhibitors, AZD4547 shows potent preclinical activity in gastric adenocarcinomas with FGFR2 amplification and other gastrointestinal tumors." (PMID 32934314, 2020). "It is a selective FGFR1, 2, 3 tyrosine kinase inhibitor with potent preclinical activity in FGFR2-amplified gastric adenocarcinoma SNU16 and SGC083 xenograft animal models, together with the patient-derived cells (PDCs)." (PMID 31242658, 2019). "Fibroblast growth factor receptor 2 (FGFR2) has been identified as a predictive biomarker for unfavorable prognosis of gastric adenocarcinoma." (PMID 28002800, 2017). "As the result, we demonstrated that FGFR2 high-expression and SPRY2 low-expression were significantly associated with unfavorable prognosis of gastric adenocarcinoma." (PMID 28002800, 2017). "In our study, the expression of SPRY family and FGFR2 was detected with IHC in gastric adenocarcinoma tissues to examine their different expressive abundance." (PMID 28002800, 2017). "Advanced Gastric Adenocarcinoma (Including adenocarcinoma of the lower third of the esophagus or the gastro-esophageal junction) with FGFR2 polysomy or gene amplification." (PMID 27409839, 2016). "Tissue microarray analyzed that HER2, EGFR, MET and FGFR2 predominances were respectively observed in 10.1, 13.9, 16.1 and 22.9% of the gastric adenocarcinomas." (PMID 27738318, 2016). "For instance, the prognostic significance of HER2 and MET protein expression level, FGFR2 gene amplification, and downstream mediators pS6 and pERK was evaluated for their potential utility as biomarkers in patients with gastric adenocarcinoma." (PMID 28536405, 2015). "However, minimal activities were achieved against tumours harbouring actionable aberration(s) in FGFR1‐3, including FGFR1‐amplified SqCLC and gastric adenocarcinoma with FGFR2 polysomy or gene amplification." (PMID 33655556, 2021). "HER2, FGFR2 and c-Met expression was analyzed in gastric adenocarcinoma cell lines." (PMID 27437872, 2016). "The cancers in which FGFR gene amplifications are most frequent include bladder urothelial carcinomas (FGFR1), squamous cell lung cancer (FGFR1), head and neck squamous cell cancer (FGFR1), uterine carcinosarcoma (FGFR3), breast adenocarcinoma (FGFR1), and gastric adenocarcinoma (FGFR2)." (PMID 26224133, 2015). "In a cohort of 950 patients with treatment-naïve gastric adenocarcinoma, 63.1% of tumors expressed at least one receptor tyrosine kinase (HER2, EGFR, MET, FGFR2), while 22.7% of these simultaneously expressed multiple biomarkers." (PMID 41303727, 2025). "Genomic amplification of FGFR1 and FGFR2 has been reported in 3–4% of EAC samples and appeared to confer a poor prognostic in gastric adenocarcinoma." (PMID 33105560, 2020).
gastric adenocarcinoma (continued). "In summary, we detected a series of biomarkers in 104 cases of gastric adenocarcinomas, including SPRY family and an identified biomarker-FGFR2." (PMID 28002800, 2017). "The mRNA levels of FGFR2 and SPRY2 were detected by quantitative PCR in 11 samples of gastric adenocarcinoma, including tumor tissues, adjacent tumor tissues and invaded lymph nodes." (PMID 28002800, 2017). "As the result, we demonstrated that both FGFR2 high-expression and SPRY2 low-expression indicated poorer prognosis of gastric adenocarcinoma." (PMID 28002800, 2017). "In our study, we investigated the expression of FGFR2 and SPRY family in 104 gastric adenocarcinoma cases and evaluated their clinical significance, including correlations with clinicopathologic factors and prognostic value." (PMID 28002800, 2017). "AZD4547 has been used in clinical trials of gastric adenocarcinoma, and Erdafitinib (BalversaTM, Janssen Pharmaceutical Companies) and BGJ398 (Infigratinib) was or will be approved by FDA for treatment of tumor with FGFR2 alterations." (PMID 34551773, 2021). "ERBB2 amplification for anti-ERBB2 inhibitor treatment in breast and gastric adenocarcinomas, EGFR amplification for anti-EGFR inhibitors, MET amplification for MET tyrosine kinase inhibitors, and FGFR2 amplification for FGFR2 phosphorylation inhibitors have been reported as predictive markers." (PMID 23936009, 2013). "Moreover, FGFR2 high-expression (P = 0.031, 5-year survival rate: 52.2% vs. 35.9%) and SPRY2 low-expression (P = 0.020, 5-year survival rate: 43.2% vs. 61.3%) were also demonstrated to be biomarkers for poorer prognosis in gastric adenocarcinoma." (PMID 28002800, 2017). "UWG02CTC also showed higher expression than UWG01CTC of targetable pathways including EGFR, FGFR2, HER-2 (ERBB2), and MET, as well as key genes in the JAK/STAT pathway, genes which overexpression are frequently reported in gastric adenocarcinomas but not gastrointestinal neuroendocrine cancers." (PMID 31953491, 2020).
gastric tumors (22 papers, 2012 to 2025). "Of all tumors with identified FGFR alterations, gastric tumors registered as the fourth highest at 12.2% (31/254), with 7.9% (20/254) of those having FGFR2 alterations." (PMID 41303727, 2025). "Twenty-six gastric tumors (5.6%) and 21 esophageal adenocarcinomas (4.9%) showed FGFR2 amplification." (PMID 36416959, 2023). "FGFR2 genetic amplification was observed in 19% (63/338) of stomach tumor samples from TCGA (cohort #1: dataset #1)." (PMID 31881796, 2019). "Our analysis revealed that most gastric tumors presented hypo/demethylation of both FGFR2 and ESRP1 promoters." (PMID 31881796, 2019). "This bias towards FGFR2-IIIb is particular to stomach tumors, as both isoforms present similar RNA expression levels in normal stomach, revealing a tight control of this process in normal tissue as opposed to cancer." (PMID 31881796, 2019). "Approximately 5–10% of gastric tumors harbor an amplification of the fibroblast growth factor receptor 2 (FGFR2) gene." (PMID 31076567, 2019). "CD44 knock-down decreased the level of FGFR2 expression and inhibited gastric tumor growth, whereas CD44 activation led to upregulation in FGFR2 expression." (PMID 29747682, 2018). "A recent study demonstrated that monoclonal antibodies to FGFR2 IIIb and FGFR2 IIIc isoforms successfully inhibited the growth of gastric tumor xenografts." (PMID 22701813, 2012). "Future studies are needed to evaluate whether the co-expression of FGF1 and FGFR2 may characterize a specific tumor subtype, such as FGFR2-amplified gastric tumors or aggressive neuroendocrine tumors." (PMID 40806365, 2025). "The reported prevalences of FGFR2 amplification and overexpression in gastric tumors vary: amplification was observed in 11.5% (7/61) of cases in one cohort, while overexpression of FGFR2 has been observed in 16.2% (612/3782) of cases, going as high as 42% (73/173) in one cohort." (PMID 41303727, 2025). "The sex ratio of FGFR2-amplified gastric tumors was comparable to the overall cohort." (PMID 36416959, 2023). "In summary, our study systematically evaluated the kinases and associated signaling pathways modulating cell response to FGFR inhibition, and for the first time, demonstrated that targeting ILK would enhance the effectiveness of AZD4547 treatment of gastric tumors with amplifications of FGFR2." (PMID 31076567, 2019). "We first explored CNVs in both FGFR2 and ESRP1 loci and found that these genes were frequently amplified or co-amplified in gastric tumors." (PMID 31881796, 2019). "Previously, receptor tyrosine kinase genomic alterations were detected in 20.6% of cases, affecting ERBB2, FGFR2, and MET, suggesting potential benefit from targeted therapy including MET-amplified gastric tumors and ERBB2 base substitutions." (PMID 27384994, 2016). "We previously demonstrated the clinicopathological significance of several cancer-associated molecules including fibroblast growth factor receptor 2 (FGFR2), transforming growth factor-beta 1 (TGFβ1), C-X-C chemokine receptor 2 (CXCR2), CXCR4, and phospho-Smad2 expressed at primary gastric tumors." (PMID 35650563, 2022). "Our genomic analysis revealed FGFR2 amplification exclusive to the primary gastric tumor and not present in the metastasis." (PMID 25315765, 2014).
urothelial carcinoma (22 papers, 2020 to 2025). A malignant neoplasm derived from the transitional epithelium of the urinary tract (urinary bladder, ureter, urethra, or renal pelvis). "Erdafitinib has been approved for treating urothelial carcinoma patients with FGFR2/FGFR3 mutations,23and clinical studies are underway for other solid tumors." (PMID 39583123, 2024). "Erdafitinib has been approved for patients with urothelial carcinoma harboring FGFR2 or FGFR3 mutations." (PMID 39421453, 2024). "In the phase II BLC2001 trial, erdafitinib brought an ORR of 40% to patients with urothelial carcinoma susceptible to FGFR3 or FGFR2 genetic alterations whose diseases progressed during or following at least one line of prior platinum‐containing chemotherapy." (PMID 36254250, 2022). "In addition to the presence of FGFR3 amplification and mutations in urothelial carcinoma, FGFR2/3 fusions have also been detected." (PMID 33655556, 2021). "Erdafitinib was approved as a first-line treatment of urothelial tumors bearing FGFR2/3 fusion or mutants and for second-line therapy of metastatic or unresectable urothelial carcinoma." (PMID 37681152, 2023). "A phase I study (NCT05242822) evaluates KIN-3248 in patients with advanced tumors, including iCCA and urothelial carcinoma, harboring FGFR2 and/or FGFR3 genomic alterations." (PMID 37681152, 2023). "Erdafitinib, a tyrosine kinase inhibitor (TKI) of FGFR, was approved by the USA FDA in April 2019 for advanced urothelial carcinoma with actionable FGFR2/FGFR3 alterations as the first molecularly targeted therapy." (PMID 34160364, 2021). "While FGFR alterations other than FGFR2/3 point mutations or fusions have not yet been approved as predictive biomarkers in urinary tract carcinomas, these were reported in the anticipation of potential future evidence supporting their therapeutic value." (PMID 41097827, 2025). "Erdafitinib is a pan-FGFR inhibitor with a quinoxaline core which was granted accelerated approval by the FDA for the first-line treatment of urinary bladder tumors with FGFR2/3 mutant or FGFR2/3 fusion and the second-line treatment of metastatic or unresectable urothelial carcinoma." (PMID 34732230, 2021). "Potentially actionable genomic alterations included FGFR2/3, ERBB2, and PIK3CA, and alteration frequencies of these genes in resected MIBC from IMvigor010 were similar to the prevalence in advanced-stage urothelial carcinoma based on the FoundationCORETM dataset." (PMID 37601688, 2023).